RN7SL431P (RNA, 7SL, cytoplasmic 431, pseudogene)
Gene: Miscellaneous RNA gene on chromosome 1 (154,166,245 to 154,166,549, reverse strand). Ensembl gene ENSG00000264384.
Homologues: Orthologues: chimpanzee Metazoa_SRP (99% identical), macaque Metazoa_SRP (95% identical). Paralogues in human: RN7SL1 (83% identical), RN7SL2 (83% identical), RN7SL3 (81% identical), RN7SL566P (81% identical), RN7SL660P (80% identical), RN7SL14P (80% identical), RN7SL45P (80% identical), RN7SL186P (79% identical), RN7SL492P (79% identical), RN7SL678P (79% identical), RN7SL712P (79% identical), RN7SL127P (79% identical), and 700 more.